TLR3 (toll like receptor 3)
Diseases named in the same sentence as TLR3 in open-access papers (continued):
Sharing a sentence is not in itself a finding about the gene and the disease.
acute respiratory distress syndrome (7 papers, 2021 to 2025). Progressive and life-threatening pulmonary distress in the absence of an underlying pulmonary condition, usually following major trauma or surgery. "Recent evidence suggests that airway epithelial TLR3 is responsible for driving IFN-β production in response to IAV infection, as determined by genetic mapping of TLR3 associated mutations in children who acquire severe IAV-induced Acute Respiratory Distress Syndrome (ARDS)." (PMID 34777390, 2021). "IAV infection leads to pneumonia or acute respiratory distress syndrome (ARDS) in humans carrying the SNPs rs5743313/CT, rs5743313, L412F, P554S/P680L, and rs3775291/rs3775290 in TLR3 gene." (PMID 39057788, 2024). "In LPS and polyinosinic:polycytidylic acid (POLY I:C)-induced acute lung injury (ALI)/acute respiratory distress syndrome (ARDS) models, CGA counteracts the inflammatory and oxidative stress in human airway epithelial cells and in BALB/c mice through targeting the TLR4/TLR3/NLRP3 inflammasome axis." (PMID 38612964, 2024).
fungal infections (7 papers, 2017 to 2025). "In fungal infection, Carvalho and co-workers showed that mice treated with fungus-derived RNA induced an effective immune response against Aspergilloses, via TLR3." (PMID 30687643, 2018). "Interestingly, it was previously shown in a mouse model, that TLR3 deletion (TLR3 −/−) increased the level of secreted pro-inflammatory cytokines upon fungal infection of the lungs compared to the wild type." (PMID 40995100, 2025). "Indeed, TLR3−/− mice are more susceptible to Aspergillus infection than are control mice, and people with mutations in key TLR3 and TLR4 signaling components are susceptible to various fungal infections." (PMID 29358941, 2017). "In recent years, the role of intracellular pattern recognition receptors (TLR3, TLR7, TLR8, and TLR9) has become increasingly important in the pathophysiology of some mycoses, such as paracoccidioidomycosis, cryptococcosis, aspergillosis, and candidiasis." (PMID 37233274, 2023). "Contrary to other fungal infections, in paracoccidioidomycosis (PCM) TLR3 is used as an escape mechanism by P. brasiliensis, generating greater susceptibility to the disease." (PMID 33194839, 2020). "In recent years, the role of intracellular pattern recognition receptors (TLR3, TLR7, TLR8, and TLR9) has become increasingly important in the pathophysiology of some mycoses, as paracoccidioidomycosis, cryptococcosis, aspergillosis, and candidiasis." (PMID 33194839, 2020). "In this section, we will discuss the role of TLR3, TLR7, and TLR9 in the main fungal infections, such as candidiasis, aspergillosis, paracoccidioidomycosis, cryptococcosis, and histoplasmosis." (PMID 33194839, 2020). "However, the role of TLR3 in paracoccidioidomycosis (PCM), which is a deep mycosis, is not clear." (PMID 30687643, 2018).
Insulin resistance (7 papers, 2015 to 2024). Increased resistance towards insulin, that is, diminished effectiveness of insulin in reducing blood glucose levels. "Additionally, data obtained from 80 human adipose tissue biopsies showed a limited association of TLR-3 gene expression levels with various metabolic abnormalities including insulin resistance and adipose tissue inflammation." (PMID 25867514, 2015). "Palmitic acid, one of the most abundant components of PO, was associated with inflammation via the activation of toll-like 2 and 3 receptors (TLR2 and TLR3) and nuclear factor kappa b (NF-κB)-mediated cytokine synthesis, insulin resistance, and NPY expression." (PMID 39125278, 2024). "Signaling through Tlr3 and Tlr4, which lie upstream of Irf3, induced insulin resistance in murine adipocytes, while Irf3 knockdown prevented insulin resistance." (PMID 39683552, 2024). "Although TLR3 is highly expressed in adipocytes, the contribution of TLR3 to insulin resistance is enigmatic." (PMID 31582899, 2019). "In an in vitro study of human cells, defects in TLR3 expression and latent endoribonuclease activation lead to decreased mitochondrial manganese superoxide dismutase expression and insulin resistance in muscle cells of obese individuals." (PMID 31582899, 2019). "In contrast, we identified decreased expression of selected genes involved in insulin resistance in adipose tissue, including TLR3, FOS, and PRL, which could induce insulin sensitivity." (PMID 26089598, 2015). "Moreover, we observed no clear associations in humans, suggesting that TLR-3 has a limited role in mediating adipose tissue inflammation and the development of insulin resistance." (PMID 25867514, 2015). "Next, we tested whether TLR-3-/- mice were protected from HFD-induced insulin resistance." (PMID 25867514, 2015). "TLR3/4-IRF3 activation induced insulin resistance in murine adipocytes, while IRF3 knockdown prevented insulin resistance." (PMID 39384770, 2024). "In contrast, four genes such as IL10RA, TLR3, FOS, and PRL demonstrate strong inverse correlations with insulin resistance." (PMID 26089598, 2015).
leishmaniasis (7 papers, 2015 to 2021). Infectious disease that is transmitted through the bite of hematophagous female phlebotomine sand flies. "TLR3 binds dsRNA in mammalian cells and was shown to play a critical role in disease exacerbation in leishmaniasis when the infecting Leishmania strain harbors a mycovirus." (PMID 32873760, 2020). "In leishmaniasis, it has been shown than a Leishmania RNA virus can be recognized by the host Toll-like receptor 3 (TLR3) to subvert the host immune response and promote parasite persistence leishmaniasis in mice." (PMID 29895639, 2018). "TLR2 and TLR3), which are popular targets in many diseases including leishmaniasis." (PMID 26660865, 2015). "Additionally, we found that SFSV and L. major co-infection resulted in an exacerbation of leishmaniasis in vivo, and by using endosomal (Toll-like receptor) TLR3, and MAVS knock-out mice, deduced that SFSV’s hyperinflammatory effect was TLR3- and MAVS-dependent." (PMID 34310619, 2021). "Taken together, these data indicate that regardless of the species and individual variations, the presence of LRV in New-World Leishmania influences inflammasome activation by a TLR3/TRIF/IFN-β/ATG5 axis, which is critical for the outcome of Leishmaniasis." (PMID 31754185, 2019). "Although we showed the essential role of TLR3, we could not formally exclude the role of other PRRs in leishmaniasis such as the RIG-like receptors (RLRs) and various members of the NOD-like receptors (NLRs)." (PMID 29487860, 2018). "However, MKP_P and TLR3 upregulation when combined with the inhibition of the adapter molecule SHC_T, a positive regulator of the MAPK cascade, can act as a useful combinatorial target in leishmaniasis treatment." (PMID 26660865, 2015).
lupus nephritis (7 papers, 2016 to 2025). Glomerulonephritis in the context of systemic lupus erythematosus. "TLR3 plays a key role in immune-mediated lupus nephritis by inducing sustained type I interferon activation." (PMID 37273692, 2023). "A recent study on human lupus nephritis found renal tubular epithelial cells to be the main producers of IFNα, at the same time as IFNα induced expression of TLR3 in the same cells." (PMID 29190833, 2017). "Interestingly, TLR3 activation does not induce B cell activation or produce anti-DNA antibodies, suggesting that TLR3-mediated lupus nephritis progresses through a B-cell independent mechanism." (PMID 39988665, 2025). "TLR3 ligation in human mesangial cells promotes the secretion of the neutrophil chemoattractant CXCL1 and CXCL1 is also expressed in diagnostic biopsies from patients with lupus nephritis but not in biopsies of patients with IgA nephropathy." (PMID 29650017, 2018).
multiple sclerosis (7 papers, 2013 to 2025). A progressive autoimmune disorder affecting the central nervous system resulting in demyelination. "Further studies found a colocalization of stathmin with TLR3 on astrocytes, microglia, and neurons in multiple sclerosis-affected human brains." (PMID 25788877, 2015). "During the inflammatory process of multiple sclerosis, TLR3 and stathmin were colocalized on the surface of astrocytes, neurons and microglia." (PMID 23548575, 2013). "The use of TLR3 agonists to license MSC has been reported by numerous groups in addition to ours, for application to suppression of inflammatory diseases such as multiple sclerosis." (PMID 40861855, 2025). "In the present study, we evaluated the immunomodulatory effect of murine MSCs after treatment with TLR3 and TLR4 agonists in vitro and in a mouse model of multiple sclerosis." (PMID 27724984, 2016).
oral cancer (7 papers, 2018 to 2024). "In contrast, high TLR3 expression is associated with poor prognosis in prostate, breast, lung, ovarian, gastric, esophageal and oral carcinomas." (PMID 37894949, 2023). "TLR3 was also reported as a potential biomarker for advanced oral cancer and associated with worse overall survival." (PMID 34531911, 2021). "Toll-like receptor 3 (TLR3) stimulation of oral cancer cells can cause tumor progression, which is evidenced by the fact that the stimulation of TLR3-expressing oral cancer cells lines (buccal OC2 cancer cells) was found to lead to tumor progression via the production of immunosuppressive factors." (PMID 34422810, 2021). "TLR3 agonists were also investigated in necrotic tumor fluids from five oral cancer patients and three mouse tumor grafts." (PMID 37894949, 2023). "Our data demonstrate that single release of either cIAPs or c-FLIP brake is sufficient to overcome resistance of human lung and oral cancer cell lines to TLR3-mediated apoptosis." (PMID 30158588, 2018). "TLR3 is overexpressed in both HNC and squamous cell carcinoma, and the TLR3 rs3775291 polymorphism mutation genotype is associated with poor survival in patients with oral cancer." (PMID 39403369, 2024). "The 14-3-3ζ proteins promote immunity by regulating TLR-3 signaling through TICAM-1 pathway and immune responses through Stat3 signaling in oral cancers." (PMID 29966317, 2018).
psoriasis (7 papers, 2018 to 2025). An autoimmune condition characterized by red, well-delineated plaques with silvery scales that are usually on the extensor surfaces and scalp. "Psoriatic keratinocytes are susceptible to viral RNA intermediates, and activation of TLR3 leads to increase of proinflammatory cytokines related with psoriasis." (PMID 32461989, 2020). "Our results indicate that the induction of autophagy may attenuate TLR3-mediated immune responses in human epidermal keratinocytes, thus providing novel insights into the mechanisms underlying the development of inflammatory skin diseases including psoriasis." (PMID 32461989, 2020). "Summing up, we showed in in vitro epidermis models that the specific activation of TLR2 or TLR3 in keratinocytes induced the expression of psoriasis markers, especially of chemokines that are related to neutrophil recruitment." (PMID 40995100, 2025). "In this work, we strived to shed more light on the role of TLR2 and TLR3 in keratinocytes for psoriasis and evaluate both receptors as a potential target for psoriasis therapies." (PMID 40995100, 2025). "In this work, we demonstrated a strong correlation between TLR2 and TLR3 activation in keratinocytes and expression of psoriasis markers." (PMID 40995100, 2025). "To analyze the role of TLR2 and TLR3 in psoriasis, we used 3D in vitro epidermis models for all experiments which mimic the complex stratification of the human skin." (PMID 40995100, 2025). "We demonstrated that treatment of in vitro epidermis models with the TLR2 agonist Pam2CSK4 and the TLR3 agonist poly(I:C) induced the expression of the psoriasis marker S100A7." (PMID 40995100, 2025). "Although the initial levels of psoriasis markers were clearly higher in TLR3 KO epidermis models compared to the wild type models, they did not significantly further increase after treatment with poly(I:C)." (PMID 40995100, 2025). "TLR3-induced interferon production serves as a common mechanism underlying Type 1 diabetes mellitus (T1DM) and psoriasis." (PMID 39988665, 2025). "Further studies should be performed in other skin resident cells (LCs, melanocytes, and keratinocytes) expressing TLR7 upon TLR3 activation during psoriasis with AZT." (PMID 33510592, 2021). "In addition to S100A7 and p-STAT3, the expression profiles of further psoriasis associated secreted immune mediators of the wild type and TLR2 or TLR3 KO epidermis models after stimulation with Pam2CSK4 or poly(I:C) were investigated with a multiplex assay." (PMID 40995100, 2025). "This indicates that the role of TLR3 in psoriasis is presumably more complex." (PMID 40995100, 2025). "Similarly, in psoriasis, dsRNA-induced activation of TLR3 in keratinocytes induces IFN-β mRNA expression, promoting dendritic cell activation and maturation." (PMID 39988665, 2025). "Thus, TLR2 and TLR3 activation in keratinocytes individually contributes significantly to inducing the release of cytokines and other immune modulators characteristic for a psoriasis like inflammation in 3D epidermis models." (PMID 40995100, 2025). "Furthermore, poly (I: C), a TLR3 agonist, could attenuate the inflammatory reaction in psoriasis-like mouse models." (PMID 30341238, 2018). "In TLR2 and TLR3 KO epidermis models the treatment with TLR2 or TLR3 agonists did not induce the expression of psoriasis markers." (PMID 40995100, 2025).
Stroke (7 papers, 2013 to 2025). Sudden impairment of blood flow to a part of the brain due to occlusion or rupture of an artery to the brain. "The totality of TLR3 signaling is widely explored in the meta‐analysis section; therefore, our focus will be on other TLRs which play a critical role in stroke." (PMID 35510663, 2022). "Although activation of TLRs signaling worsens stroke injury, some reports suggest that the TLR3 activation by polyinosinic‐polycytidylic acid (poly I:C) mediates innate immune responses and thereby provides neuroprotection." (PMID 35510663, 2022). "Our results suggest that similar to stroke and hypoxia-ischemia, the mechanisms of cell death in the developing brain after TLR3 activation diverge by sex." (PMID 30971945, 2019). "Preconditioning with Poly‐IC activates the TLR3 signaling pathway via TRIF, thereby inducing neuroprotection in an experimental stroke model." (PMID 40406905, 2025). "Sex differences in the mechanisms of cell death have been described after brain injury secondary to stroke and hypoxia-ischemia and here, we provide preliminary evidence that these differences may also occur in response to TLR3 activation in the neonatal brain." (PMID 30971945, 2019). "Similarly, in a mouse stroke model, TLR3 and TLR9 did not confer protection to neural cells during middle cerebral artery occlusion." (PMID 30809253, 2018). "Studies of stroke using animal models suggest that activation of TLRs by the release of endogenous ligands contributes to tissue injury and indicates that TLR2 and TLR4, but not TLR3, contribute to this pathological process." (PMID 23589665, 2013).
tick-borne encephalitis (7 papers, 2014 to 2025). Tick-borne encephalitis is caused by an arbovirus of the Flaviviridae family (tick-borne encephalitis virus, TBEV), transmitted principally by the bite of the Ixodes ricinus tick. "Polymorphisms in the chemokine receptor 5 (CCR5) and toll-like receptor 3 (TLR3) genes were found to be risk factors for clinical tick-borne encephalitis in the Lithuanian population." (PMID 31122248, 2019). "Polymorphisms in chemokine receptor 5 (CCR5) and toll-like receptor 3 (TLR3) genes were found to be a risk factors for clinical tick-borne encephalitis in the Lithuanian population." (PMID 29297316, 2017). "TLR3 (rs3775291) is a well-studied polymorphism and has found to be associated with several other infectious diseases including severe tick-borne encephalitis (TBE) virus infection, human immunodeficiency virus (HIV), and herpes simplex virus (HSV)-2 infections." (PMID 34113509, 2021). "Although remarkable knowledge has been gained from HSE patients with inborn defects in the TLR3 pathway, in the recent past, TLR3-pathway risk alleles have been implicated in underlying pathogenesis of tick-borne encephalitis (TBE)." (PMID 34696494, 2021). "We previously reported that a nonfunctional chemokine receptor 5 (CCR5) and a functional Toll-like receptor 3 (TLR3) predispose adults to clinical tick-borne encephalitis (TBE)." (PMID 25226020, 2014). "It has been shown in the Russian population that five SNPs in OAS2 and OAS3 genes, as well as two SNPs in IFNL3/IL28B gene and polymorphisms in the TLR3, CD209, and IL10 genes were associated with predisposition to severe forms of tick-borne encephalitis." (PMID 29297316, 2017).
type 1 diabetes (7 papers, 2012 to 2025). "We investigated the association of the TLR3 variants, rs13126816 and rs3775291, with the autoimmune endocrine disorders, Addison’s disease (AD) and type 1 diabetes (T1D) in the Polish population." (PMID 26318769, 2016). "As it is hypothesised that viruses play a role in the pathogenesis of type 1 diabetes, it might be interesting to investigate the role of TLR-3 in the pancreas." (PMID 25867514, 2015). "Several studies have showed a link between TLR-3 induced islet inflammation and type 1 diabetes." (PMID 25867514, 2015). "RV is a double-stranded RNA virus and therefore it is of interest that beta cells express the innate immune toll-like receptor 3 (TLR3) for double-stranded RNA, as well as the double-stranded RNA sensor, IFN-induced helicase 1, which is a susceptibility gene for type 1 diabetes." (PMID 25181416, 2014). "Variations in the TLR3 gene may be found in patients with type 1 diabetes, Steven-Johnson syndrome, and toxic epidermal necrolysis." (PMID 23151015, 2012).
viral myocarditis (7 papers, 2009 to 2023). Myocarditis that is caused by an infection with a viral agent. "Recently, TLR3 polymorphisms in a patient population were associated with an increased occurrence of viral myocarditis and DCM." (PMID 22013485, 2012). "Taken together, these observations suggest that therapies aimed at re-establishing TLR3 signaling or its functional consequences may provide an effective means to protect susceptible patients from suffering the fatal consequences of viral myocarditis." (PMID 19122812, 2009). "Furthermore, since TLR3 is clearly implicated in immune activation in viral myocarditis, exploration of OGN and TLR3 and 5 interactions is needed to unravel the precise effect of OGN on cardiac inflammation in different cardiac diseases." (PMID 27878326, 2017). "Meanwhile, STAT1 phosphorylation of PAR2 overexpressed CFs has been shown to be significantly decreased following PAR2 and TLR3 agonist stimulation, suggesting that PAR2 negatively regulates TLR3-dependent IFN-β production and promotes viral myocarditis." (PMID 36827455, 2023). "TLR3 is involved in viral recognition and in mounting antiviral type II interferon response; mice lacking TLR3 developed severe viral myocarditis highlighting the protective action of this TLR in CVB3 infection." (PMID 28707261, 2017). "Unlike its critical role in viral myocarditis and distinctly different from the mechanisms of cardioprotection observed in TLR3 knockout mice, poly(I:C) preconditioning exhibits myocardial protection via phosphorylation of TLR3 and its enhanced interaction with PI3K and downstream molecules." (PMID 33154351, 2020).
bronchiolitis (6 papers, 2014 to 2025). Inflammation of the bronchioles characterized by swelling of the bronchioles and mucus accumulation. "A previous study from the present cohort offered preliminary evidence that the wild TLR3 rs3775291 genotype increased the risk for repeated post-bronchiolitis wheezing." (PMID 28592890, 2017). "We have earlier studied the TLR1rs5743618, TLR2 rs5743708, TLR3 rs3775291, TLR4 rs4986790 and TLR6 rs5743810 polymorphisms, and reported their associations with bronchiolitis and post-bronchiolitis outcomes." (PMID 27498757, 2016).